PDCD1 (programmed cell death 1)
Diseases named in the same sentence as PDCD1 in open-access papers (continued):
Sharing a sentence is not in itself a finding about the gene and the disease.
tumor (continued). "However, it is worth mentioning that the expression of the immune checkpoints PDCD1, LAGLA3, and TIGIT is higher in tumor-specific Trm cells than in Tcm cells or Tem cells." (PMID 38779662, 2024). "Notably, immune checkpoint inhibitors (ICIs), particularly anti‐programmed cell death 1 (PD1) and anti‐programmed cell death ligand 1 (PD‐L1), have shown clinical efficacy in clinical tumour immunotherapy." (PMID 38594879, 2024). "In both datasets, LAG3 was found to be expressed mainly on exhausted CD8+ T cells (CD8Tex cells) rather than on tumor cells or other types of immune cells compared and was also co-expressed with PDCD1." (PMID 38277212, 2024). "Additionally, immune checkpoint molecules (e.g., CCR4, CD27, CD274, CD68, CTLA4, PDCD1, and PDCD1LG2) were significantly upregulated in the AERShigh group (all p < 0.01), suggesting potential impairment of the anti-tumor immune response." (PMID 39464883, 2024). "Overexpression of ALYREF and YBX1 was accompanied by the upregulation of immune checkpoint inhibitors (such as CD276 and PDCD1) and downregulation of immune checkpoint stimulants (such as CX3L1, ITGB2, CD40LG and SELP), which promoted evasion of immune surveillance by these tumor cells." (PMID 38238581, 2024). "When assessing tumor-infiltrating exhausted CD8+ T cells with exhaustion unique gene markers, such as Lag3, Tigit, Havcr2, Ctla4, and Pdcd1, we observed that the Lag3 and Tigit levels in the MnBuOE/RT group were significantly lower than those in the other groups (p < 0.05)." (PMID 38671924, 2024). "However, to our surprise, our results demonstrated that EPHX4 was significantly negatively correlated with CD274, PDCD1, IDO1 and LAG3, which all attenuate anti-tumor immunity and escape destruction by the immune system." (PMID 38663041, 2024). "In our study, we found that high PSMB2 expression may induce the upregulation of CD274, CTLA4, HAVCR2, LAG3, PDCD1, PDCD1LG2 and SIGLEC15, which are molecules on immune cells that facilitate tumor immune escape." (PMID 38467767, 2024). "High MAEL expression was associated with few CD8+ T cells in tumor center (P=0.040), tumor margin (P=0.016), and total area (P=0.026), high TMB (P=0.013), and low expression of PDCD1 (P=0.003) and CTLA4 (P=0.049) rather than CD274 (P=0.12)." (PMID 38301040, 2024). "However, this study noted decreased anti-tumor immunological microenvironments and decreased CTLA4 and PDCD1 expression in NSCLC patients with Nrf2-activating MU." (PMID 37794491, 2023). "The effectiveness of anti-programmed cell death 1 (PD1) immunotherapy, a promising pathway in the treatment of gliomas, is correlated with the expression of the programmed death ligand 1 (PD-L1) and the tumor immune microenvironment cell components." (PMID 37476838, 2023). "Depleted and dysfunctional tumor-infiltrating lymphocytes (TILs) in HNC cases are characterized by upregulation of several checkpoint markers, such as programmed cell death 1 (PD-1), lymphocyte-activating gene 3 (LAG-3), and cytotoxic T-lymphocyte-associated protein 4 (CTLA-4)." (PMID 37511510, 2023). "Likewise, another study showed that the CRISPR/Cas9-mediated deletion of the PDCD1 gene increased the cytotoxic effect of CD19 targeting CAR-T cells and reduced tumor growth in a xenograft tumor model." (PMID 38201467, 2023). "With the in-depth exploration of the relationship between the immune system and cancer, immunotherapy targeting programmed cell death 1 (PD1)/programmed cell death-ligand 1 (PD-L1) and cytotoxic T-lymphocyte antigen 4 (CTLA4) has revolutionized tumor treatment." (PMID 37202800, 2023). "We found that pre-treatment gene expression levels of PDCD-1, but not CD274 (gene that encodes PD-L1), was statistically significantly associated with reduction in tumor size." (PMID 37188783, 2023).
tumor (continued). "Moreover, a recent first-in-human trial confirmed that adoptive transfer of T cells retrovirally transduced with a tumor-reactive TCR and edited at the TRAC, TRBC and PDCD1 loci by CRISPR/Cas9 was safe and feasible." (PMID 37849763, 2023). "Thereby, a constant antigen stimulation of the T cells in the tumor microenvironment (TME) leads to a high expression of LAG3 and of other co-inhibitory receptors on T cells, such as PDCD1, promoting immune escape in tumors and exhaustion of T cells that lose their effector functions." (PMID 37215135, 2023). "Initially, it was shown that the clinical activity of the monoclonal antibody pembrolizumab, by blocking programmed cell death 1 (PD1) on T cells and other immune cell populations, enhanced the cytotoxic killing of tumor cells, improving survival rates in metastatic MSI CRCs." (PMID 37372349, 2023). "As a ligand for the inhibitory receptor PDCD1, CD274 could mediate anti-tumor immune escape by regulating the activation threshold of T cells and limiting T-cell effector responses." (PMID 37663248, 2023). "tumor cells could escape immunosurveillance via interacting with immune modulator markers, such as TNFSF9, CTLA4 and PDCD1, which are known as important molecules for cancerigenesis or cancer immunotherapy." (PMID 37013511, 2023). "Additionally, a strong correlation between RHBDF2 upregulation and immune checkpoint genes (PDCD1, CD274, LAG3, CTLA4, TIGIT, HAVCR2) was observed in HCC, and these immune checkpoint genes can contribute to tumor immune escape and promote tumor progression." (PMID 36943228, 2023). "In addition, the relationship between NOLC1 and CD274, PDCD1, and PDCD1LG2, which are important immune checkpoints for tumor immune escape, was also explored." (PMID 37670166, 2023). "A significant positive association occurred between five types of immune cells and CSF3 expression (r > 0.30, p < 0.05), including cytotoxic T cells, Th17 cells, neutrophils, and DC cells, all immune cells having a favorable correlation with PDCD1 and CSF3 showed anti-tumor properties." (PMID 37644514, 2023). "Furthermore, tumor-infiltrated CD8+ T and CD4+ T cells in the allografts highly expressed the activation/exhaustion markers, such as GZMB, GZMK, PDCD1, LAG3, HAVCR2, and CTLA-4." (PMID 37980406, 2023). "In the process of APOBEC mutagenesis, the increased expression of important immune checkpoint molecules, including PDCD1, TIGIT, HAVCR2, LAG3 and IDO1, and the elevated CYT score, which serves as cytotoxic effects and anti-tumor response, were highly suggestive of better immunotherapy response." (PMID 37215984, 2023). "Moreover, risk scores were negatively related to the expression of CD274, CTLA4, ICOS, LAG3, PDCD1, and PDCD1LG2 and negatively correlated with CD8+, CD4+, and Treg tumor-infiltrating immune cells." (PMID 37674251, 2023). "The secretion of IL-12 from the PDCD1 locus enhanced the effector function of NY-ESO-1 TCR-T cells and promoted their proliferation during repetitive tumor challenges in vitro, leading to superior anti-tumor activity in xenograft models." (PMID 36793716, 2023). "The CD4/CD8 ratio and programmed cell death-1 (PD-1) expression of T cells in primary tumor tissues, tumor-draining lymph nodes (TDLNs) and non-draining lymph nodes (NDLNs) were assayed with flow cytometry." (PMID 35633411, 2022). "BA is thus designed to target tumors via colocalized, simultaneous inhibition of two key immunosuppression pathways in the tumor microenvironment: the PD-L1/programmed cell death 1 protein immune checkpoint pathway (targeting PD-L1) and immunosuppressive axis of TGF-β during tumor pathogenesis." (PMID 36066618, 2022). "In addition, the correlation between LOXL2 expression and immune checkpoint markers (CD274, PDCD1, and CTLA-4) suggested a role for LOXL2 in immune regulation of tumor immunity." (PMID 36254230, 2022).
tumor (continued). "Therefore, in terms of regulating the tumor microenvironment, ADRB2, SMAD4, FCER2 and PDCD1 had vital predictive significance in the immunotherapy of NSCLC." (PMID 36005189, 2022). "Effector genes such as GZMB, GZMH and KLRG1 were the marker genes in clonotypes shared by all tissues, while the clonotypes present only in tumor showed upregulated T-cell exhaustion genes (HAVCR2, LAG3, CTLA4, TIGIT, PDCD1, and ICOS) and activation genes (SELL and TNFRSF9)." (PMID 36185254, 2022). "Various immune checkpoints are the mature targets in tumor immunotherapy, like PD1/PD-L1 (Programmed Cell Death 1/ Programmed Cell Death Ligand 1), CTLA4 (Cytotoxic T-Lymphocyte Associated Protein 4) and LAG3 (Lymphocyte Activating 3), are in ongoing clinical trials." (PMID 35831836, 2022). "We further revealed that ADAMTS12 expression was positively correlated with immune checkpoint proteins (such as PDCD1, CD274, LAG3, and CTLA4), immunosuppressive genes, chemokines, and chemokine receptors in most tumor types." (PMID 35280819, 2022). "To comprehensively inspect the immune microenvironment of HCC TME, we firstly compared gene expression of immune inhibitory checkpoint molecules between tumor tissues and normal (peri-tumor) tissues, including CD274, CTLA4, HAVCR2, LAG3, PDCD1, PDCD1LG2, TIGIT, and SIGLEC15." (PMID 35444645, 2022). "CD274, PDCD1 and CTLA4 are vital immune checkpoints that are responsible for tumor immune escape." (PMID 35637248, 2022). "However, tumor-infiltrating CD4+ and CD8+ T cells showed much higher percentages of CD69, CCR5, and PDCD1 expression when compared with circulating T cells." (PMID 36301668, 2022). "Besides, the expression of cell exhaustion-related genes, including PDCD1, CTLA4, LAG3, and TIGIT, was upregulated in several tumors, indicating that UBE2S was intensely involved in tumor evasion via different mechanisms." (PMID 35578600, 2022). "Indeed, poor prognosis and high hazard ratios were found associated with PTEN-low/miRNA-low high RhoA signalling in the BL-1 tumours, AKT1 copy gain/high mRNA expression in the BL-2, and high programmed cell death 1 (PD1) expression in IM." (PMID 36077812, 2022). "Regarding the involvement of IRF family genes in tumor immunosuppression, the present study found that IRF family genes were significantly correlated with the immune checkpoint genes (PDL1 and its receptor PDCD1) in HNSC." (PMID 35664436, 2022). "Immune checkpoints (ICs) generally refer to key inhibitory factors of the immune system, including programmed cell death 1 (PD-1 or CD279) and its ligand programmed cell death 1 ligand 1 (PD-L1 or CD274) that control the T cell response and fate during tumor immunity." (PMID 36741695, 2022). "To evaluate the utility of both Pdcd1 primer sets and anti-PD-1 FACS ab clones to detect tumor cell-intrinsic PD-1 across additional melanoma lines, we assessed PD-1 gene and protein expression in a series of YUMM murine melanoma variants with defined oncogenic mutations." (PMID 35864188, 2022). "Cytotoxic T Lymphocyte antigen 4 (CTLA-4), Programmed Cell Death 1 (PD-1), and Programmed Cell Death Ligand 1 (PD-L1, also known as B7-H1 or CD274) pathways are the best known immune checkpoint pathways for immune responses within the tumor microenvironment." (PMID 33823818, 2021). "In the meantime, the elevated expression of ICGs such as PDCD1, CD274, CTLA4 may also modulate tumor response to immunotherapy." (PMID 35116021, 2021). "Importantly, POLD1 expression was associated with immune checkpoint molecules, including CD274, CD80, CD86, CTLA4, PDCD1 and TCGIT, and facilitated an immune-excluded tumor microenvironment." (PMID 34868924, 2021). "PD-1 (also called PDCD1, CD279) is expressed on immune cells, especially tumor specific T cells, while PD-1 ligand PD-L1 (also called B7-H1, CD274) is expressed on tumor cells as an “adaptive immune mechanism” to escape anti-tumor response (Han, Liu & Li, 2020)." (PMID 34458019, 2021).
tumor (continued). "In this trial, median gene expression of PDCD1 was zero and the majority of patients (85%) did not present PDCD1 immunoexpression in tumor cell or in the TIL." (PMID 33591648, 2021). "Furthermore, co-expression between PDCD-1 and LAG-3 in environments containing either tumor, self-Ag, or chronic infection can result in T cells with poor effector function." (PMID 34544358, 2021). "Finally, in a syngenic murine model of OC, we observed the therapeutic benefit of CDDP plus programmed cell death-1 (PD-1) inhibitor, which enhanced the cytolytic activity of CD8+ T cells and inhibited tumor growth." (PMID 34091590, 2021). "In our samples, the mRNA levels of CCL5, FASLG, EOMES, and PDCD1 in tumor tissues were significantly higher than those in normal tissues." (PMID 34531849, 2021). "Programmed cell death protein 1 (PD-1/PDCD1), programmed cell death 1 ligand 1 (PD-L1/CD274), and cytotoxic T lymphocyte antigen 4 (CTLA-4) are vital immune checkpoints that play important roles in tumor immune escape." (PMID 34938665, 2021). "Interestingly, in PDCD1-TGFBR2 DKO CAR T-cells, tumor eradication was more efficient in comparison to TGFBR2-edited CAR T-cells, emphasizing the importance of synergizing the knockout of multiple T-cell inhibitory pathways." (PMID 34446084, 2021). "Therefore, we evaluated the relationship between the expression of immune inhibitory molecules (TIGIT, PDCD1LG2, PDCD1, LAG3, HAVCR2, CTLA4, and CD274) in the immune ignorant, immune inactive, and hot tumor subtypes." (PMID 33777927, 2021). "These genes were defined as the tumor reactive signature (TRS), including co-inhibitory receptors (CTLA4, PDCD1, TIGIT and HAVCR2), reactive markers (CD38 and ENTPD1), effector molecules (NKG7 and PRF1), tumor necrosis factor TNFRSF9 and critical exhaustion-related regulator TOX." (PMID 34804045, 2021). "(I–K) Flow cytometric analysis of the expressions of programmed cell death-1(PD-1) (I), PD-1 and Tim3 (J), and CTLA-4 (K) in CD8+ T cells in the tumor of Cd300afl/fl (n = 4 in I, n = 3 in J and K) and Cd300afl/fl;ItgaxCre (n = 6 in I, n = 5 in J, n = 4 in K) mice." (PMID 34751648, 2021). "Concerning prototypical immune checkpoints, expression of CD274 (PDL1) and PDCD1LG2 (PDL2), which encode ligands for PDCD1 (PD1), expressed in tumor-infiltrating T cells, was virtually absent in the profiled human GBM tumors." (PMID 34917090, 2021). "Although TILs often comprise a heterogeneous mixture of tumor-specific and many irrelevant bystander T cells, tumor-reactive CD8+ TILs may be characterized by the upregulation of programmed cell death 1 (PD-1) and CD39 expression." (PMID 34185709, 2021). "However, both AURKA and AURKB expression were significantly inversely correlated with markers for T-cell infiltration of the tumor: CD3E, CD4, CD8A, LCK, PDCD1 and IFNG." (PMID 33123754, 2021). "Importantly, we observed that in lung tumor-infiltrating CD4+ T cells from CD4/ALK4-KO mice, Tox and Tox2 demonstrated significantly enriched binding on the -23 kb enhancer sequence of Pdcd1, compared to their WT counterparts." (PMID 34548096, 2021). "Moreover, CD163 expression was positively correlated with most gene markers of these tumor-infiltrating immune cells in both the TCGA and CGGA cohorts, including CD8A, CD8B, STAT6, STAT5A, and PDCD1." (PMID 34395626, 2021). "Nevertheless, the expression of ICM leads to immune escape of tumor cells and some of these ICMs (particularly the cytotoxic T lymphocyte antigen (Ag)-4 (CTLA-4), programmed cell death-1 (PD-1) and its ligand (PD-L1)) are now being blocked by monoclonal antibodies (mAbs)." (PMID 37425217, 2020). "Furthermore, core fucose modification of programmed cell death-1 (PD-1) has been found to be essential for its surface expression on T cells, which also demonstrates that FUT8 is involved in anti-tumor immunity." (PMID 31936666, 2020).
tumor (continued). "It has been known that immunosuppressive Tregs express cytotoxic T-lymphocyte-associated protein 4 (CTLA-4) at higher levels and a combination of programmed cell death 1 (PD-1) and CTLA-4 blockades increases tumor-infiltrating effector T cell and reduces tumor-infiltrating Tregs." (PMID 33352665, 2020). "The inflamed TME was characterized by higher expression of PDCD1, CTLA4, CD28, (PD-L1) CD274, PD-L2, and lower tumor mutation burden than non-inflamed TME." (PMID 32528935, 2020). "For example, insertion of IL-12p70 into the IL-2Rα or PDCD1 gene locus produced T cells with antigen-dependent IL-12p70 production, resulting in enhanced anti-tumor function without significant toxicities." (PMID 32570906, 2020). "T cells express the programmed cell death-1 (PD-1) immune checkpoint receptor; this receptor binds the programmed cell death ligands 1 and 2 (PDL-1; PDL-2) that are expressed by the tumor microenvironment, preventing the immune surveillance of tumor cells." (PMID 32824391, 2020). "Immune checkpoint inhibitors (ICI) target key points in the immune system’s tolerance to tumors in order to enhance the anti-tumor response, such as cytotoxic T lymphocyte antigen 4 (CTLA4), programmed cell death 1 protein (PD1) and its ligand programmed cell death 1 ligand 1 (PDL1)." (PMID 33066179, 2020). "The expression of genes encoding immune checkpoint molecules, such as programmed cell death ligand 1 (PD‐L1), programmed cell death 1 (PD‐1), cytotoxic T‐lymphocyte antigen (CTLA)‐4, and CD8A, which is a marker of tumor‐infiltrating lymphocytes, was investigated." (PMID 31240875, 2019). "Finally, for exhausted signature genes, two inhibitory receptors PDCD1 and CTLA4 were found to be specifically demethylated within tumor-reactive CD8+ T cells." (PMID 31892342, 2019). "Discoveries of programmed cell death 1 (PD-1) and cytotoxic T-lymphocyte antigen 4 (CTLA-4) were major breakthroughs, and the disclosure of their roles in tumor immune environments has led to the creation of ICI, which caused a paradigm shift in cancer treatments." (PMID 31752884, 2019). "In line with this and unlike reported for basal squamous tumors in the TCGA publication, CDKN2Ahigh tumours also do not show an elevation of PDCD1, CD274 and CTLA4 expression." (PMID 30258198, 2018). "The programmed cell death 1/programmed cell death ligand 1 (PD1/PD-L1) cell signaling pathway is closely related to the functioning of the immune system, which is currently a research hotspot in the field of tumor immunotherapy." (PMID 28662185, 2017). "Using array-based analyses, significant differences in the CpG-methylation patterns between tumor tissues and matched controls were observed for CTLA4 and PDCD1 (PD1) (FDR < 0.01): NSCLC tumors exhibited a decreased degree of CpG-methylation in these loci compared to tumor-free tissues." (PMID 28503213, 2017). "Most recent are targeting two immuno-checkpoint receptors; CTLA4 (cytotoxic T-lymphocyte-antigen 4), PD-1 (programmed cell death 1) and its ligand PDL1, and show a remarkable efficacy against certain tumors, through re-activating cytotoxic T (Tc) cell mediated tumor killing." (PMID 28148223, 2017). "T-cell immunoglobulin mucin-3 (Tim-3) and programmed cell death-1 (PD-1) are important negative immune regulatory molecules involved in viral persistence and tumor metastasis." (PMID 25950468, 2015). "PDCD1 and CTLA4 are T cell surface molecules that can inhibit anti-tumor T cell responses." (PMID 24782321, 2014). "Notably, compared with the PD‐L1− tumor group, the upregulated differentially expressed genes (DEGs) in the CD8‐C2‐Texterm subset from PD‐L1+ tumor group included exhaustion‐related genes such as HAVCR2, CXCL13, PDCD1, TIGIT, LAG3, BATF, GNLY, and CTLA4." (PMID 41194450, 2026). "Interestingly, CXCL6 and other ARGs also showed negative correlations with checkpoints like VEGFB, KIR2DL1, LAG3, CTLA4, PDCD1, and IFNG, indicating they may promote immune surveillance and anti-tumor responses." (PMID 40943183, 2025).